UBE2C (ubiquitin conjugating enzyme E2 C)
Diseases named in the same sentence as UBE2C in open-access papers (continued):
Sharing a sentence is not in itself a finding about the gene and the disease.
cancer (continued). "UBE2C could be an effect biomarker for cancer prognosis prediction and metastasis monitor." (PMID 37803076, 2023). "Notably, pan-cancer analysis also identified UBE2C as an oncogene in various tumors." (PMID 37535572, 2023). "Moreover, the heat map showed that the DEGs in two cancer cell lines with interfering UBE2C was involved in the cell cycle, suggesting that UBE2C participating in the cell cycle may be a common regulatory mechanism of pan-cancer development." (PMID 36292703, 2022). "This positive correlation may indicate the critical role of UBE2C as a tumour oncogene during the cell cycle through enhancing the G1/S and G2/M transitions that prevent cancer apoptosis and promotes tumour cell proliferation via controlling the PI3K/AKT/mTOR signalling pathway." (PMID 35124721, 2022). "However, in IAC, the most malignant UBE2C + cancer cells gradually dominate, which may explain why the prognosis of IAC is poor." (PMID 36434043, 2022). "Moreover, KAT2A and E2F1 could promote cell proliferation and the migration of cancer cells by enhancing the expression of UBE2C." (PMID 36292703, 2022). "In addition, based on our previous study, the analysis of tumor tissue single-cell transcriptome data showed that the expression of UBE2C has a significant up-regulation trend in cancer cell clusters (CS), such as CS4 of CRC, CS2 of LC, CS4 of OV, CS3 of PDAC, and CS5 of SCC." (PMID 36292703, 2022). "In addition, both immune relevance analysis and GSEA showed that UBE2C might participate in immune response in many cancers." (PMID 34950739, 2021). "Thus, UBE2C can serve as a biomarker for prognosis, and blocking UBE2C may be a beneficial strategy for cancer therapy." (PMID 34199813, 2021). "The AUC was 0.9794, indicating that UBE2C could discriminate ESCC tissues from non-cancer tissues." (PMID 34488675, 2021). "Therefore, it might be helpful for understanding the potential mechanism of UBE2C in tumorigenesis and screening the potential therapeutic targets for pan-cancer to explore the role of UBE2C in TME." (PMID 34950739, 2021). "Finally, GSEA was used to annotate the potential function of UBE2C across 33 cancers." (PMID 34950739, 2021). "According to the differentially expressed genes obtained from GEPIA2 and gene expression profiles gained from UCSC Xena, UBE2C was identified as a differentially expressed gene in 33 cancer types, which indicated that UCE2C might play an important role in carcinogenesis." (PMID 34950739, 2021). "In addition, UBE2C expression was significantly upregulated in 28 tumor-infiltrating lymphocytes, 45 immune stimulators, 24 immune inhibitors, 41 chemokines, 18 receptors, and 21 MHCs in pan-cancer." (PMID 34858987, 2021). "Therefore, overall, our findings showed that UBE2C might influence immune cell infiltration, which makes it a predictive biomarker for immunotherapy in cancer patients." (PMID 34858987, 2021). "In addition, UBE2C was correlated with CD276 in many cancers." (PMID 34950739, 2021). "Moreover, UBE2C played roles in cell growth, migration/invasion and cancer stemness in OSCC cells." (PMID 32899896, 2020). "Our data highlight the UBE2C network as one of the major protein networks involved in cancer and further investigation on their function in tumors might shed light onto new therapeutic strategies for cancer." (PMID 31067633, 2019). "Moreover, UBE2C protects cancer cells from autophagic death." (PMID 30914455, 2019). "Therefore, it is likely that aberrant UBE2C overexpression, leading to changes in ubiquitination, might be involved in uncontrolled cell proliferation, which is one of the main features of cancers." (PMID 31067633, 2019). "However, further functional studies are required to clarify the role of UBE2C in cancers." (PMID 31067633, 2019). "Therefore, UBE2C has been considered as an important functional gene in cancer development." (PMID 30116193, 2018).
cancer (continued). "In previous reports, the downregulation of UBE2C could increase the expression of E-cadherin and decrease the expression of Slug, Twist, and Snail49–51, which are transcriptional drivers for vimentin in human cancer." (PMID 29904125, 2018). "In addition, high expression of UBE2C correlates with cancer progression or a poor prognosis." (PMID 27528424, 2016). "Moreover, we showed that UBE2C mRNA expression was able to accurately discriminate ESCC tissue from both healthy esophageal and histologically normal tumor surrounding tissues, pointing out its role as a diagnostic marker for this cancer." (PMID 27588470, 2016). "Furthermore, UBE2C as a biomarker of efficacy of cancer chemotherapy should be explored." (PMID 24699941, 2014). "Our analysis revealed 9 shared genes, with UBE2C, POLQ, RAD51, and HOXB7 being up-regulated and EDNRB, GPD1L, F10, SORBS2, and CXCL12 down-regulated in both cancers." (PMID 41790655, 2026). "In BC tissues, TAP1, PILRA, UBE2C, TMEM51, and MKI67 were significantly upregulated, while the expression levels of SPP1 and CENPF remained unchanged between cancer and adjacent tissues." (PMID 41328437, 2025). "We searched for other potential overlaps and found that CXCL2, LIF, UBE2C, KRT5, ICAM1, and CXCL8 were significantly upregulated in STIC lesions identified in patients with cancer compared with adjacent normal epithelium." (PMID 40689422, 2025). "Upregulated UBE2C expression was significantly correlated with OS and DFS of 10 and 9 types of cancer patients." (PMID 38577722, 2024). "Nonetheless, the expression pattern of UBE2C in AML and its relationship with the prognosis of AML patients remained unexplored comprehensively towards correlating their expression with the cancer progression." (PMID 38637730, 2024). "In summary, the present study demonstrates that UBE2C is a differential expressed gene in 28 types of cancer, playing a strong prognostic role in OS and DRF of patients with most of the cancers." (PMID 38577722, 2024). "Correlation analysis was conducted between Ki67 and UBE2C in pan-cancer through the GEPIA2 database, and it was found that UBE2C was moderately to highly correlated with the Ki67 index in 33 tumors except for CESC and COAD (R > 0.4)." (PMID 38370368, 2024). "Recent studies showed that the high expression of UBE2C has correlation with poor OS and DFS of cancer patients." (PMID 38577722, 2024). "It was found that CDK1 overexpression in adrenocortical carcinoma cell (ACC) lines locked ACC cells at the G2/M checkpoint by interacting with UBE2C and AURKA/B, promoting cancer cell proliferation and inducing epithelial mesenchymal transition (EMT)." (PMID 39830349, 2024). "Our data suggest that combined inhibition of UBE2C and PLK1 can more significantly strongly attenuate the proliferation, migration, colony formation and other malignant phenotypes of pan-cancers while inducing more intense cell cycle arrest and apoptosis." (PMID 37958642, 2023). "In summary, we identified a new UBE2C/PLK1-ACLY axis that plays an essential role in the cell cycle and pan-cancer cells." (PMID 37958642, 2023). "The common (pan-cancer) genes are MMP11 (+), C7 (-), ANGPTL1 (-), UBE2C (+), IQGAP3 (+) and ADH1B (-)." (PMID 36802377, 2023). "The gene expressions of most ubiquitination-related regulators were low, while the gene expressions of UBE2C and ubiquitin-conjugating enzyme E2T (UBE2T) were extremely high in multiple types of cancer." (PMID 37540295, 2023). "To further analyze the relationship between UBE2C and PLK1, we performed a correlation analysis in tumor tissue samples across 33 cancer types, which showed that the correlation coefficient between UBE2C and PLK1 was 0.30–0.93." (PMID 37958642, 2023). "To validate the effect of UBE2C and PLK1 on the progress of cancer development, we transfected si-PLK into stable knockdown UBE2C cell lines for 72h." (PMID 37958642, 2023).
cancer (continued). "In this study, we found a positive correlation between the expression of UBE2C and PLK1/BIRC5 in the Cancer Genome Atlas (TCGA) database, revealing a potential combination therapy candidate for pan-cancer." (PMID 37958642, 2023). "Next, we analyzed the expression levels of UBE2C and PLK1 in different pathological stages and found that UBE2C was significantly overexpressed in stage III and IV in 17 types of cancers." (PMID 37958642, 2023). "The relationship between UBE2C overexpression and tumor stages in UCEC suggested the pro-cancer role of UBE2C in UCEC development." (PMID 37803076, 2023). "In our previous study, we found that UBE2C was co-regulated by lysine acetyltransferase 2A (KAT2A) and E2F transcription factor 1 (E2F1) to promote cell proliferation and migration in pan-cancer." (PMID 37958642, 2023). "In this study, we found that UBE2C and PLK1 were significantly highly expressed in more than 13 cancer tissues." (PMID 37958642, 2023). "Various studies have shown that the cell-cycle-related regulatory proteins UBE2C, PLK1, and BIRC5 promote cell proliferation and migration in different types of cancer." (PMID 37958642, 2023). "HE staining further confirmed obvious cancer metastasis in the lung tissues of mice treated with oe-ALKBH5 + sh-NC, whereas the metastasis was decreased in the presence of oe-ALKBH5 + sh-UBE2C." (PMID 36551544, 2022). "Owing to the inhibitory effect of UBE2C on the proliferation of THCA cells, this study also explored its influence on the apoptosis of cancer cells." (PMID 35332135, 2022). "From the result of correlation analysis in tumor tissue samples across 11 cancer types and cell line samples in CCLE, we found that the correlation coefficient between the two in KAT2A, E2F1, and UBE2C was 0.037–0.82." (PMID 36292703, 2022). "Given the clinical and functional significance of KAT2A/E2F1/UBE2C in pan-cancer, we concluded that KAT2A/E2F1/UBE2C and its associated pathway were crucial for cancer carcinogenesis, and targeting this pathway may be pivotal in the prevention or treatment of pan-cancer." (PMID 36292703, 2022). "For all 56 hub gene candidates, only CHEK1 and UBE2C were found to be significantly correlated with BRCA patient survival and differentially expressed between cancer and normal specimens." (PMID 35903365, 2022). "Based on our findings, UBE2C expression mediates HIF‐1α activation, increasing glycolysis pathway activation and the invasion/migration abilities of cancer cells." (PMID 35615976, 2022). "Intriguingly, UBE2C, mediated by ALKBH5, links apoptosis (type I PCD) with autophagy (type II PCD), which coregulates autophagic apoptosis in cancer cells." (PMID 35090469, 2022). "Since some cancer types lack TCGA normal controls in TIMER2.0, we used GEPIA2.0 to investigate UBE2C expression in these cancers by matching TCGA normal and GTEx data as controls." (PMID 35804892, 2022). "Ubiquitin-conjugating enzyme E2 C (UBE2C) has been illustrated to facilitate proliferation, survival, invasion, and EMT in cancer." (PMID 33435156, 2021). "To examine the gene expression of UBE2C, we first used the TIMER database to analyze the levels of UBE2C in various cancers." (PMID 34858987, 2021). "Student’s t test revealed that the positive signal for UBE2C in ESCC was concentrated in the cytoplasm, with an average expression value (8.63889 ± 2.47112) significantly higher than in than non-cancer tissues (6.42958 ± 1.77611, p < 0.001)." (PMID 34488675, 2021).
cancer (continued). "The ROC curves of the six combined data sets revealed 5 of 6 datasets with AUC > 0.9, suggesting significant differences in the expression of UBE2C in the ESCC versus the control group, and that the cancer tissues showed significantly high expression." (PMID 34488675, 2021). "Among the genes affected by RRBP1, UBE2C, SHC1, and CLDN7 have all been recently identified as highly relevant targets in other cancers." (PMID 34445467, 2021). "In addition, our study showed that UBE2C was significantly relevant to TME in many cancer types and the TME played a crucial role in tumor initiation, progression, and metastasis process and also threw light on therapeutic efficacy suggesting that UBE2C might a potential immunotherapeutic target." (PMID 34950739, 2021). "To elucidate the biological functions of UBE2C in various cancers, we utilized the LinkedOmics database to perform KEGG-enriched analysis for UBE2C in different cancer types." (PMID 34858987, 2021). "The profile of expression of UBA1, UBE2C, UBE2T, UBE2O, and CCNF in BRCA seemed to support their involvement in cancer initiation and progression." (PMID 34201347, 2021). "Further, graph centrality measures suggested the importance of upregulated genes such as BIRC5, UBE2C, BUB1B, KIF20A and PTH1R in cancer." (PMID 34728699, 2021). "More studies will be focused on investigating how UBE2C regulating these cancer markers including ALDH1A2, CD44, CD166 and EpCAM and the relationship between these cancer markers for cancer stemness in vitro." (PMID 32899896, 2020). "The deletion of UBE2C notably reduced the level of phosphorylated aurora kinase A via Wnt/β–catenin and PI3K/Akt and results in inhibition of the cancer growth and metastasis." (PMID 32703154, 2020). "Of note, LY6D, ST3GAL4, ASS1, PTP4A3 (also named PRL-3), UBE2C (also named UBCH10), and E2F3 are novel oncogenes and biomarkers whose overexpression are related to metastases, migration, or proliferation of NSCLC and other cancers." (PMID 27935865, 2017). "As the hallmarks of malignant tumors are characterized by abnormal cell growth and apoptosis, in our study, we performed CCK-8 and Annexin V staining assays to determine the effects of UBE2C deletion in U87-MG and U251 cells." (PMID 28767320, 2017). "The human Ub-conjugating enzymes (E2), UBE2C and UBE2S, cooperate with E3 Ub ligase anaphase-promoting complex/cyclosome (APC/C) to regulate the cell cycle in cancers." (PMID 25734985, 2015). "Some of them, such as UBE2C, CASP3, CCND1/2, STAT3, JAK2 and MMP-9, have been used as markers of cancer malignancy." (PMID 26603105, 2015). "In the end, we identified six genes (DLGAP5, DSCC1, SSBP1, UBE2C, SNRPD1, and SMO) with a vital role in prevention of cell death in both cell lines and hence six potential drug targets for silencing in cancer therapy." (PMID 23251412, 2012). "As undifferentiated tumors are more aggressive and metastatic, we can suggest that UBE2C and AURKA are overexpressed in malignant tumors." (PMID 20630075, 2010). "Among the 16 common cancer biomarkers identified as highly predictive by the previous study which did not include NPC samples, 6 genes (CYC1, MIF, LAMB3, TSTA3, TUBB2, and UBE2C) were found to be highly expressed in NPC by the study." (PMID 18570662, 2008). "Additionally, Single-cell functional analysis showed that UBE2C was positively correlated with cell cycle, proliferation, DNA damage, EMT, DNA repair, invasion and differentiation in some cancers." (PMID 38370368, 2024). "Therefore, this study aims to elucidate the potential mechanism by which UBE2C affects the proliferation of LUAD and even pan-carcinoma, as well as its crucial role in cancer diagnosis, targeted therapy and immunotherapy." (PMID 38370368, 2024).
cancer (continued). "A pan-cancer study indicated that KAT2A was found to cooperate with E2F1 and be recruited by E2F1 to the UBE2C promoter for elevating the expression of UBE2C by increasing the acetylation level of H3K9 to promote cell proliferation and the migration of cancer cells." (PMID 39546499, 2024). "Although previous studies have analyzed the role of UBE2C in pan-cancer 28, there is a lack of further research on the mechanism of UBE2C in pan-cancer and its prognostic and immunotherapeutic value." (PMID 38370368, 2024). "It was also shown that UBE2C overexpression is only found in cancer cells, and not in normal tissues." (PMID 37958776, 2023). "In addition, it has been reported that the expression levels of UBE2C and MYBL2 show a strong positive correlation in a variety of cancers." (PMID 37840753, 2023). "Additionally, we found that the knockdown of UBE2C and PLK1, respectively, can reduce the proliferation and migration capacity, and induce the cell cycle arrest and apoptosis of pan-cancer cell lines, which was consistent with the results of previous studies." (PMID 37958642, 2023). "The results suggest that the synergistic effect of the cell-cycle-related genes UBE2C, PLK1, and BIRC5 may promote the development of pan-cancer by affecting cell metabolism." (PMID 37958642, 2023). "The results suggest that both UBE2C and PLK1 may promote the occurrence and development of pan-cancer by separately influencing the cell cycle." (PMID 37958642, 2023). "In addition, based on our previous study, the analysis of tumor tissue single-cell transcriptome data showed that the expressions of UBE2C and PLK1 have a similar significant upregulation trend in cancer cell clusters (CSs)." (PMID 37958642, 2023). "Furthermore, the experimental validation of the expression and role of UBE2C was performed on HGSOC tissues and cancer cell lines." (PMID 35804892, 2022). "Apart from that, UBE2C and CDC20 can also be found in other cancers." (PMID 36385010, 2022). "Additionally, the result of the expression levels of UBE2C in pathological stages showed that it was significantly highly expressed in stage III and IV in 10 types of cancer." (PMID 36292703, 2022). "Significantly altered functions, pathways, and gene networks revealed alterations in several key genes and cancer-related pathways that may have importance for NSCLC transformation, including FAM83A, ZNF696, UBE2C, RECK, TIMM50, GEMIN7, and XPO5." (PMID 35309509, 2022). "Growing evidence has demonstrated that UBE2C plays a critical role in cancer progression, but there is no study focusing on the prognosis, upstream regulation mechanism, and immunological roles of UBE2C across diverse tumor types." (PMID 34858987, 2021). "We also explored the correlation between the UBE2C expression and MSI of human cancer, and the results showed that UBE2C expression was markedly positively correlated with the MSI in SARC, MESO, UVM, and ACC and negatively correlated with the MSI in SKCM and THYM." (PMID 34858987, 2021). "Furthermore, to determine UBE2C expression in diverse cancer cell lines, using the analysis of the CCLE database, we show that UBE2C expression was upregulated in various cancer cell lines." (PMID 34858987, 2021). "In addition, about 20 cancer types were relevant to resting memory CD4 T cells, such as KIRC which UBE2C, and resting memory CD4 T cells were negatively correlated." (PMID 34950739, 2021). "Three tumor suppresser genes, including CYLD, ATM, and TSPYL2, showed a negative correlation with UBE2C in several cancers with a similar moderate to strong negative correlation for them in the following cancers: LUSC, READ, UCEC, OV, and UCS." (PMID 31067633, 2019). "Regarding BRCA1 and BRCA2, both of these genes showed similar strong positive correlations with UBE2C in different cancers, but a negative correlation was observed for BRCA1 in THCA and for BRCA2 in TGCT." (PMID 31067633, 2019).